NGFR (nerve growth factor receptor)
Diseases named in the same sentence as NGFR in open-access papers (continued):
Sharing a sentence is not in itself a finding about the gene and the disease.
tumor (continued). "Importantly, in the NGF‐NGFR communication, NGF was secreted from tumor cells while NGFR was expressed in the T cells." (PMID 38204220, 2024). "Precise monitoring of intra-tumor heterogeneity during phenotype transitions over time was achieved by flow cytometry using stable cell lines established with a MITF promoter-GFP reporter construct and combined with NGFR membrane staining." (PMID 38519642, 2024). "TNBC cells rely on the significant upregulation of NGFR expression to facilitate their growth as tumor spheres in a non-adhesive environment." (PMID 37566075, 2023). "As an additional benefit, NGFR-spaced CAR T cells, which proved to be highly functional in animal tumor models, could be tracked with antibodies directed against NGFR." (PMID 38090558, 2023). "S3, D and E), indicating that tumor cell NGFR does not change the composition of NK cell subpopulations but rather imposes a general suppression on NK cell activity." (PMID 36638181, 2023). "Collectively, these data designate NGFR as a negative feedback regulator of p73 tumor suppressive activity." (PMID 32285119, 2020). "This tumor subpopulation is characterized by high expression levels of the RTK NGFR but, unexpectedly, not AXL." (PMID 32770055, 2020). "We also detected an increased expression of NGFr transcripts in the blood of Mock-4T1 tumor-bearing mice, though the results were not statistically significant (data not shown)." (PMID 30333826, 2018). "VDAC1-based peptide tumor treatment eliminated GSCs, as reflected in the marked decrease in the expression levels of all tested stem cell markers, namely Sox2, Nestin, CD133, Klf4, S100B and NGFR." (PMID 28412744, 2017). "Further, inhibition of NGFR reduces tumor growth, indicating a functional role of this receptor; however, the mechanisms by which NGFR confers enhanced tumor formation are not known." (PMID 27683113, 2016). "In normal oral mucosa epithelium, a sub population of basal cells with stem cell-like properties has been shown to express the nerve growth factor receptor (NGFR), and recent reports indicate that NGFR contributes to the tumor-initiating capacity of a number of malignancies." (PMID 27683113, 2016). "In relation to CD90 and NGFR, there are significant differences between HGPs in relation to CD90, taking into account all the tissue available (total punch) as well as considering exclusively the tumoral part (adj p < 0.001) and the tumor compartment (adj p = 0.018)." (PMID 39563958, 2024). "In this regard, it seems conceivable that the observed CD271 expression might not entirely be attributed to the stem cell character of tumor cells but might also be found in certain differentiated cells expressing nerve growth factor receptor." (PMID 37187729, 2023). "The interactions of tumour microenvironment with ECM scaffolds usually activate cell’s membrane focal adhesion proteins and transmembrane signal receptors (TSR), epidermal growth factor receptors (EGFR), vascular endothelial growth factor (VEGFR) or nerve growth factor receptors (NGFR)." (PMID 30465280, 2018). "Next, we analyzed the enrichment of H3K27me3 and Ezh2 at the promoters of NGFR, WT1 and MME in these cell lines and human NSCs, and observed that H3K27me3 and Ezh2 were enriched at the promoters of WT1 promoter more than other two gene promoters in all these tumor lines tested." (PMID 29932419, 2018).
tumor (continued). "CD271 (also known as nerve growth factor receptor, NGFR or p75NTR) is a neurotrophin receptor that has been implicated in the paracrine growth regulation of a number of neuronal and non-neuronal tumor types." (PMID 23300742, 2012). "To verify the functionality of NGFR-enriched CD44v6 CAR-T cells, we tested them in coculture experiments with tumor cells expressing or not CD44v6." (PMID 29619024, 2018). "Of note, by stratifying the mice based on survival time, we found that mice euthanized early after tumor injection showed low numbers of circulating OVA-specific T cells and no appearance of NGFR-negative ALL." (PMID 30042420, 2018). "While NGFR-transduced cells did not respond to CXCL8, they released calcium upon stimulation with tumor supernatants, albeit 2 to 6 times less than CXCR2-transduced NK cells." (PMID 28923105, 2017). "We observed that KRAS transplant tumours had very few Sca1+/NGFR+ cells and were indistinguishable from adeno-Cre induced KRAS tumours (P=0.368)." (PMID 28387316, 2017). "For all assessed RCC tumor supernatants, the CXCL1 but not CXCL8 concentration correlated significantly (p = 0.014) with the migration of CXCR2-transduced NK cells relative to NGFR-transduced NK cells." (PMID 28923105, 2017). "The NGFR and RXRG genes were upregulated in all non-MEL, non-MES samples, suggesting their stem-like characteristics, while they were found with low expression levels in MES- and MEL-like tumours, as expected." (PMID 36765773, 2023). "Interestingly, only NGFR+ xenografts formed in nude and NOD/SCID mice, not NSG mice, were able to phenocopy parental tumours." (PMID 35740696, 2022). "On the other hand, the expression of CD166, CD133, CD44, A2B5, CD56, NGFR and DCX seemed to be higher in UA cells, but also not statistically significant, while the expression of CD9, Nestin, GFAP, CD24, PDGFRb, PDGFRa, MAP2, TUBIII, S100 were consistently high in both UA and tumor core samples and." (PMID 27605047, 2016).
cancer (166 papers, 2006 to 2025). A tumor composed of atypical neoplastic, often pleomorphic cells that invade other tissues. "This was associated with an increased mRNA level of NGFR, indicating the relevance of neuroinvasive cancer-derived EVs in mediating SC migration." (PMID 39863771, 2025). "These cells, subjected to α-KG deficiency, show increased expression of cancer persister marker, NGFR." (PMID 32483452, 2020). "Regarding the role of the NGF signaling pathway in tumorigenesis, an association between the expression of NGFR TrkA and p75NTR has been reported in various types of cancers." (PMID 28679437, 2017). "Reducing the levels of NGFR in cancer cells caused the cells to become more sensitive to some anti-cancer drugs." (PMID 27282385, 2016). "Cancer-associated pathways including NGFR, TGFB, Hippo, and Wnt were also deregulated between the HCC subgroups, implying that the differential functions were involved in HCC progression." (PMID 25521761, 2014). "NGFR acts as a tumor suppressor in most cases of cancers, causing apoptosis and suppression of metastatic invasion." (PMID 22558167, 2012). "Some of them, like Axl, EphB2, HGFR, and the nerve growth factor receptor TrkA are implicated in epithelial repair, proliferation, and cancer growth." (PMID 18167552, 2008). "TrkC and NGFR neurotrophin receptors are associated with cell death, cancer and differentiation." (PMID 33675128, 2021). "Furthermore, it is interesting to find that the cancer-associated pathways including NGFR, TGFB, Hippo, and Wnt had the differential mutations and expressions between the HCC subgroups." (PMID 25521761, 2014). "Additional research has shown that in many cancers, NGFR controls cell proliferation, invasion, metastasis, autophagy, and apoptosis." (PMID 40758712, 2025). "Pancreatic stellate cells have been reported to transiently upregulate NGFR when co-cultured with cancer cells, and NGFR+ cells are predominantly found in benign lesions such as PanIN, rather than in direct association with the bulk of malignant cells." (PMID 41006303, 2025). "For example, it has been shown that ibuprofen can increase the mRNA and protein levels of NGFR/p75NTR by inducing its promoter hypomethylation and by increasing N6-methyladenosine (m6A)-NGFR/p75NTR expression in cancer cell lines." (PMID 36834612, 2023). "Intriguingly, the NGFR-mediated changes in lipid metabolism significantly impair antimelanoma cytotoxicity of NK cells, enabling increased cancer cell survival in the circulation and metastatic homing to secondary organs." (PMID 36638181, 2023). "NGFR is expressed in various cancer types, including luminal breast cancer in rare basal-like cells that are resistant to antiestrogens." (PMID 37566075, 2023). "Depending on the cancer type, it has been reported that NGFR can act as an oncosuppressor and an oncogene." (PMID 37511924, 2023). "Through the NGF-Neurotrophic Receptor Tyrosine Kinase 1 (TrkA)-Nerve Growth Factor Receptor (NGFR) axis, Schwann cells exhibit robust chemotaxis towards neoplastic cells, in which participate in neural regeneration around cancer cells." (PMID 37524695, 2023). "One of the most well-studied cancer targets highlighted in our network analysis is the nerve growth factor receptor (NGFR)." (PMID 38132437, 2023). "There is increasing evidence that nerve growth factor (NGF) and its receptors, the neurotrophic receptor tyrosine kinase 1 (NTRK1/TrkA), the common neurotrophin receptor (NGFR/p75NTR) and the membrane receptor sortilin, participate in cancer growth." (PMID 35457078, 2022).
cancer (continued). "Because NGFR binds to diverse types of ligands in different cancers, its functions are highly dependent on the cell type." (PMID 33996571, 2021). "Repression of p73 function also manifested in both apoptosis assays and colony formation assays, as NGFR significantly reduced p73-mediated apoptosis and increased proliferation in cancer cells, as well as reduced p73-mediated inhibition of clonogenicity." (PMID 32285119, 2020). "The induction of NGFR by interferon gamma (IFN-γ) in cancer cells 76 suggests a generic stress-induced phenotype." (PMID 32483452, 2020). "Taken together, these studies indicate that a stress-induced shift to a slow-cycling state of cells expressing KDM5 and NGFR serves as a crucial step for cancer progression and therapy resistance." (PMID 32483452, 2020). "NGFR directly binds to p73 central DNA-binding domain and suppresses p73 transcriptional activity as well as p73-mediated apoptosis in cancer cells." (PMID 32285119, 2020). "We then determined that NGFR in turn counteracts p73 function in a variety of cancer cells, as the ectopic overexpression of NGFR resulted in a decreased in p73 levels, while shRNA-mediated knockdown of NGFR increased p73 levels." (PMID 32285119, 2020). "We have shown that NGFR expression is indeed induced by multiple stress factors such as drug exposure, hypoxia and glucose starvation in multiple cancer types 45, 63 and correlates with KDM5A/B expression." (PMID 32483452, 2020). "Among these genes, NGFR, PRKN, STAT3, IDH2, etc. were associated with the neuronal system and cancer pathway as the significant terms (P < 0.001)." (PMID 31708732, 2019). "The NGFR+ cells in ESCC were more likely to be the cancer stem cell, and more resistant to chemotherapy drug DDP than NGFR- cells of ESCC." (PMID 30355311, 2018). "It remains largely elusive why and how NGFR plays opposite roles in the context of different cancers." (PMID 27282385, 2016). "Previous studies showed that NGFR induces apoptosis in some cancer cells, but promotes cell survival and growth in other cancer cells." (PMID 27282385, 2016). "In line with our findings, a growing body of evidence has identified NGFR as a robust cell surface biomarker not only for neural crest stem cells, but also cancer initiating or stem-like cells." (PMID 27282385, 2016). "NGFR expression is induced in many pathological conditions, such as atherosclerosis, ischemia, diabetes and cancer." (PMID 22558167, 2012). "Additionally, Metformin was reported to suppress the proteolytic cleavage of nerve growth factor receptor (NGFR), a transmembrane protein implicated in cancer cell proliferation and metastasis, thereby contributing to apoptosis in HNSCC cells." (PMID 41156128, 2025). "However, we observed clear protein expression of ITGB7 in tumors cells at immune cell-enriched areas of Ecad+ and NGFR+ tumors, suggesting a broader function in different subtypes of metastases and cancers." (PMID 38386085, 2024). "These neurotrophin effects are mediated when binding to the cell-surface receptors like tropomyosin-related kinase receptor/tropomyosin receptor kinase A (TrkA) and p75 neurotrophin receptor (NGFR/p75NTR), of which TrkA is mainly expressed on the cancer cell surface." (PMID 39099944, 2024).
cancer (continued). "However, while these studies have mostly focused on the impact of lipids from dietary fats, we show in the present study that NGFR induces a cancer cell–intrinsic switch toward increased lipid metabolism." (PMID 36638181, 2023). "These molecules interact with receptors expressed by cancer cells, such as TrkA, TrkB, and NGFR." (PMID 37566075, 2023). "NGFR’s function continued conflicting in some cancers, probably due to the heterogeneity." (PMID 33675128, 2021). "Importantly, these cells show a dedifferentiated state characterized by high levels of cancer stem cell markers, such as NGFR and JARID1B." (PMID 33202944, 2020). "Our new findings that NGFR promotes the degradation of p73 in cancer cells led us to question whether NGFR can also suppress p73-mediated cellular outcomes." (PMID 32285119, 2020). "Therefore, inhibition of proNGF, NGF, or NGFR has been proposed as therapeutic stratagems for human malignant tumors." (PMID 28679437, 2017). "Thus, NGF signaling from nerves to cancer stem cells via NGFR expression may promote cancer stem cell renewal and proliferation." (PMID 37566075, 2023). "Our findings are novel in the sense that NGFR typically functions as a transmembrane pan-receptor involved in the initiation, development, and maintenance of the nervous system and human cancers and instead connects NGFR with the CMA, another cancer-associated pathway." (PMID 32285119, 2020). "In addition, EFNB1 and NGFR were downregulated in CD44+ cancer cells versus normal cells." (PMID 26673618, 2016). "NGFR is a transmembrane receptor with well-documented roles in promoting ERK1/2 signaling activation and cancer progression." (PMID 41315175, 2025). "The binding of NGF to NGFR/p75NTR leads to the activation of NF-kB or JNK, which mediates opposite effects on survival and apoptosis of both neurons and cancer cells, respectively." (PMID 36354700, 2022). "Among the annotated AD versus NAT top50 hypermethylated DMRs, several markers were found to be hypermethylated in various cancers including FLI1, GATA4 and NGFR." (PMID 29945573, 2018). "ESM1, one of the most up-regulated genes in the NGFR overexpressing MOC2T cells, was of particular interest given its known role in cancer progression." (PMID 27683113, 2016). "Our data indicate that CD271/NGFR is functionally active in SCCHN and that targeting CD271 with a monoclonal antibody is a potential therapeutic strategy in this cancer." (PMID 25149537, 2014).